CLU (clusterin)
Diseases named in the same sentence as CLU in open-access papers (continued):
Sharing a sentence is not in itself a finding about the gene and the disease.
dementia (continued). "In the current study, we did not observe increased plasma levels in AD subjects compared to controls and we have found that plasma clusterin levels could not discriminate AD subjects from healthy controls, nor with subjects with other dementias." (PMID 23209684, 2012). "A meta‐analysis observed that plasma clusterin concentrations were increased in people with AD dementia, but not in people with MCI or other dementias." (PMID 41517952, 2026).
Obesity (35 papers, 2014 to 2026). Accumulation of substantial excess body fat. "Clusterin (CLU), a chaperone protein, is associated with joint inflammation and synovitis, particularly in obesity." (PMID 40243895, 2025). "Circulating plasma clusterin concentrations have been associated with inflammation and increased cardiovascular risks in patients with obesity, however, the underlying mechanism remains elusive." (PMID 38396489, 2024). "Studies have shown that clusterin is associated with pro-inflammatory reactions in inflammatory myopathy, obesity, and asthma, but exerts an anti-inflammatory function in renal injury and autoimmune myocarditis." (PMID 37717073, 2023). "In obesity characterized by a body mass index above 30 kg/m2, clusterin concentrations are increased, and associated with insulin resistance and inflammatory markers." (PMID 36553017, 2022). "Obesity in both sexes, especially in males was associated with high levels of IL-6, clusterin and irisin and worsened the metabolic pattern." (PMID 33905632, 2021). "There are discrepancies about the relationship of both clusterin and irisin levels with adiposity and obesity associated insulin resistance." (PMID 33905632, 2021). "Briefly, our data revealed that, obesity in both sexes, especially in males was associated with high levels of circulating IL-6, clusterin and irisin and worsened the metabolic pattern." (PMID 33905632, 2021). "This study aimed at evaluating the circulating levels of IL-6, clusterin, and irisin in obese subjects of both sexes who had different grades of obesity and examining their sexual dimorphism and their association with insulin resistance." (PMID 33905632, 2021). "There are discrepancies about the relationship of IL-6, clusterin and irisin with obesity and obesity associated insulin resistance and also about their sexual dimorphism." (PMID 33905632, 2021). "ER stress and the expression of factors supporting the re-translocation and degradation of clusterin are more expressed in environments associated with metabolic syndrome (e.g., hyperlipidaemia, glucose-intolerance, and obesity) than in psoriasis." (PMID 32764517, 2020). "First, clusterin deficiency exacerbates WD-induced metabolic parameters in obesity and NAFLD whereas clusterin overexpression results in protective effects." (PMID 33060605, 2020). "Taken together, our findings suggest that clusterin plays an important role in the prevention and treatment of diet-induced obesity and NAFLD, two main risk factors for metabolic syndrome." (PMID 33060605, 2020). "Therefore, our study aimed at evaluating the circulating levels of IL-6, clusterin and irisin in obese subjects of both sexes who had different grades of obesity and examining their sexual dimorphism and their association with insulin resistance." (PMID 33905632, 2021). "Circulating clusterin is also negatively associated with leptin in obesity-related CVD." (PMID 33717095, 2021). "To identify whether the protective effect of clusterin in diet-induced obesity and NAFLD is associated with AMPK activation, we examined AMPK activation in the liver and eWAT." (PMID 33060605, 2020). "Therefore, LRP2 acts as a key mediator of the food intake-suppressing effects of clusterin, and its absence can cause obesity in rodents (as previously demonstrated)." (PMID 25158045, 2014). "Therefore, the circulating clusterin level may be a surrogate marker for obesity-associated systemic inflammation." (PMID 25076422, 2014). "Hence, it can be reasonably speculated that obesity-associated systemic inflammation may induce the increased production or secretion of clusterin from the liver." (PMID 25076422, 2014). "The aim of the present study is to investigate the possible association of serum concentrations of MCP-1, activin A, and clusterin with obesity or T1DM in children and adolescents." (PMID 38396489, 2024).
Obesity (continued). "Clusterin levels showed a trend towards lower values in children with T1DM or obesity compared to the control group and were negatively correlated to renal function." (PMID 38396489, 2024). "The expression of the CLU gene is increased in patients with obesity compared to lean subjects, and is decreased after bariatric surgery and subsequent weight loss." (PMID 38396489, 2024). "Among obese patients, however, plasma levels of clusterin were found to be increased as well as directly related to obesity-related metabolic disease complications, among which were insulin resistance, dyslipidemia, and hepatic steatosis." (PMID 36553017, 2022). "We also found that clusterin activates target molecules for obesity and NAFLD, namely Nrf2 and AMPK, suggesting that clusterin protects against Western diet-induced obesity and NAFLD by activating Nrf2 and AMPK." (PMID 33060605, 2020). "Many studies have shown the correlation between clusterin expression and metabolic diseases such as obesity and NAFLD." (PMID 33060605, 2020). "Here we generated transgenic mice with whole-body clusterin overexpression (wCLU-tg) and investigated the role of clusterin in Western diet-induced obesity and NAFLD." (PMID 33060605, 2020). "The present study demonstrated that clusterin protects against the pathophysiology of obesity and NAFLD by reducing body weight and fat mass, hepatic fat accumulation, and steatohepatitis." (PMID 33060605, 2020). "Clusterin is a multi-functional protein that is up-regulated in the pathogenesis of various metabolic diseases, including obesity and NAFLD." (PMID 33060605, 2020). "Recent studies have shown that plasma clusterin levels can be affected by gender, obesity, systemic inflammation, or atherogenic components of the lipid profile in AD patients." (PMID 29169407, 2017). "Many, sometimes contrasting, roles are ascribed to clusterin in obesity, metabolic syndrome and related conditions." (PMID 28120874, 2017). "Given its multifaceted role, alterations in clusterin levels may contribute to the pathophysiology of obesity and its related complications." (PMID 40943443, 2025). "Plasma clusterin was increased in overweight and obese individuals, correlated with BMI, and was suggested as a surrogate obesity marker; properdin levels and indicators of complement activation were increased in donors with a family history of T2D and suggested as markers of future risk." (PMID 36722378, 2023). "In addition to the attributed neuroprotective role, clusterin has been described as protective in the context of chronic pain, obesity, and cardiac disease." (PMID 36553017, 2022). "Furthermore, clusterin levels were higher in ICU patients with pre-existing obesity and type 2 diabetes." (PMID 36553017, 2022). "Furthermore, the previous studies aimed at evaluating the levels of clusterin and irisin in lean, overweight and obese subjects with little respect to grades of obesity." (PMID 33905632, 2021). "In this context, elevated plasma clusterin level may represent a defense mechanism to attenuate obesity related oxidative stress and inflammation." (PMID 33905632, 2021). "This suggests that clusterin may play a role in modulating appetite and contributing to obesity." (PMID 33717095, 2021). "In addition, the effects of adipocyte-derived clusterin on the AT immunoenvironment and the skewed balance of pro- and anti-inflammatory cytokines observed in human obesity is also unknown." (PMID 33717095, 2021). "Previous study has illustrated that Clusterin exhibited protective effects in NAFLD and western diet-induced obesity through activating AMPK and Nrf2." (PMID 38992588, 2024). "For the identified DEHGs for obesity, there were six previously reported genes (UGGT1, ANO6, MPEG1, PTGS1, CLU and IQGAP1) and two novel genes (LUZP6 and PLCB2) for obesity." (PMID 35568907, 2022).
Obesity (continued). "In this regard, the authors of this work proposed adipocyte-derived CLU as a novel ECM-related protein linking cardiometabolic diseases and obesity through its actions in the liver." (PMID 35203598, 2022). "Although CD14, CLU, CD99, and SAA2 have been reported to be protein markers for insulin resistance, obesity, and inflammation, our data showed that they only had a modest difference in expression level between healthy and pre-diabetic sera." (PMID 33995275, 2021). "To investigate the role of increased clusterin in WD-induced obesity and NAFLD, we generated transgenic mice with whole-body clusterin overexpression (wCLU-tg)." (PMID 33060605, 2020). "In summary, the role of clusterin expression levels on the pathophysiology of obesity and NAFLD are still uncertain, but there is a considerable correlation between clusterin and these diseases." (PMID 33060605, 2020). "For several adipokines (ANGPTL3, DLL1, chemerin, clusterin, leptin, Nampt, resistin, GPX3), we identified a close relationship with parameters of obesity (BMI, waist circumference, body fat mass), but also inflammation (hsCrP)." (PMID 24968098, 2014). "Patients with obesity defined by a body mass index above 30 kg/m2 tended to have higher clusterin levels (median 58.9 μg/mL vs. median 51.1 μg/mL in non-obese patients, p = 0.066)." (PMID 36553017, 2022). "To investigate the role of increased clusterin in diet-induced obesity and NAFLD, we generated transgenic mice with whole-body clusterin overexpression (wCLU-tg; C56BL/6J-CLUfloxed+/+ × C56BL/6JElla cre+) and confirmed that clusterin upregulation has a protective effect." (PMID 33060605, 2020). "Finally, in patients with obesity, different pubertal status, as expressed with Tanner stages, did not affect serum clusterin levels." (PMID 38396489, 2024).
Cognitive impairment (32 papers, 2012 to 2026). Abnormal cognition is characterized by deficits in thinking, reasoning, or remembering. "Three genetic polymorphisms of clusterin predisposing to cognitive impairment have been detected: rs11136000, rs2279590, and rs9331888." (PMID 38542375, 2024). "By contrast, in 2012, Thambisetty and coworkers found that in mild cognitive impairment, higher plasma clusterin levels were associated with slower rates of brain atrophy." (PMID 23209684, 2012). "Our findings suggest that the association between baseline clusterin and cognitive impairment, specifically executive function (EF), was partially mediated by longitudinal neurodegeneration as indicated by hippocampus volume, accounting for approximately 17.84% of the total effect." (PMID 37941999, 2023). "Elevated expression of the CLU gene is noted in refractory cancers, and is also associated with memory and cognitive impairment, as the structure of the brain may be altered under conditions of CLU dysregulation." (PMID 37195412, 2023). "Studies measuring protein levels in cerebrospinal fluid (CSF) revealed elevated CSF clusterin in AD cases compared with controls, and a study of non‐demented and mild cognitive impairment patients revealed increased CSF clusterin was related to amyloid β‐associated brain atrophy." (PMID 25940137, 2016). "Such a heterogenetic effects for CLU genetic variants has been reported previously by Thambisetty M and co-workers although they reported the faster rates of decline in memory among carriers of the CLU rs11136000 risk allele restricted to those who became mildly cognitive impaired." (PMID 24244428, 2013). "It has been studied that in patients with various degrees of cognitive impairment, clusterin levels are related to synaptic degeneration and are positively correlated with the level of neurogranin in the cerebrospinal fluid." (PMID 38542375, 2024). "Clusterin was previously reported to be increased in AD and mild cognitive impairment (MCI) plasma and CSF, although results are inconsistent." (PMID 37480051, 2023). "The findings revealed that baseline CSF clusterin was a predictor of longitudinal cognitive impairment in individuals with MCI, and that baseline CSF clusterin concentrations were more predictive in females under the age of 65." (PMID 37941999, 2023). "Clinically, the degree of cognitive impairment positively correlates with higher plasma levels of clusterin." (PMID 37511841, 2023). "In patients with both mild cognitive impairment and AD, clusterin levels are elevated in the brain, cerebrospinal fluid, and blood, and accordingly CLU gene expression is elevated in these pathologic conditions." (PMID 33717095, 2021). "Intraperitoneal or intraventricular administration of a short clusterin-derived peptide can decrease Abeta deposition in mouse models, as well as ameliorate cognitive defects." (PMID 33192447, 2020). "Previous studies have found that clusterin was related to cognitive impairment, however, these were among subjects with AD." (PMID 29324756, 2018). "Several characteristic properties of clusterin make it related with the pathology of cognitive impairment." (PMID 27516739, 2016). "Another possible interpretation is that increased plasma clusterin level is related to a reduced rate of atrophy as a protective factor in cognitive impairment patients." (PMID 27516739, 2016). "These lines of evidence demonstrated that neurodegenerative changes during cognitive impairment may increase clusterin expression, suggesting the beneficial role of clusterin in AD pathology." (PMID 27516739, 2016). "In APP/PS1 AD mice, it was also found that TMAO is associated with and may lead to increased levels of apolipoprotein J (or clusterin, CLU), a risk factor for AD, which increases the activity of β-secretase, which is involved in amyloid accumulation, promoting cognitive impairment." (PMID 39462700, 2024).
Cognitive impairment (continued). "Importantly, a recent report indicated that three proteins, Aβ, TREM2 and Clusterin, display an early increase in patients with severe Aβ pathology but no detectable cognitive defects and in patients with mild cognitive impairment, with continuous accumulation in AD." (PMID 33250918, 2020). "In addition, higher clusterin was related also to severity of cognitive impairment." (PMID 29324756, 2018). "Thus, whether plasma clusterin serves as a deleterious substance or reflects a neuroprotective response during progress of cognitive impairment warrants further research." (PMID 27516739, 2016). "Thus, the association of plasma clusterin with prevalence and severity of AD and its correlation with brain atrophy in mild cognitive impairment suggests that plasma clusterin may be a potential marker of disease progression in AD." (PMID 23209684, 2012). "Moreover, taking account of the HspB8 results, these findings suggest that the cell‐type specific dysregulation of clusterin distinguishes between individuals with or without cognitive deficits and is specific to clusterin and not simply reflecting an underlying reactive process." (PMID 31386770, 2020). "We tested the correlations between plasma APL1β28 and clusterin levels using scores from the MMSE, which is the most widely used screening instrument for cognitive deficits." (PMID 26503441, 2015). "In the context of neurodegenerative disease, clusterin levels were also examined by mass spectrophotometry from blood samples, based on the results of which it was possible to distinguish ALS patients with cognitive deficits and controls." (PMID 38184629, 2024). "However, in the mild cognitive impairment (MCI) population, our analysis suggested that the impact of clusterin on cognitive measures was partially mediated by neurodegeneration, specifically in the hippocampus." (PMID 37941999, 2023). "Levels of clusterin are elevated in the CSF and plasma of LOAD patients; indeed, plasma clusterin has been suggested as a biomarker for AD, correlating with disease severity and progression from mild cognitive impairment (MCI) to AD in some studies." (PMID 34946939, 2021). "Further, in ALS mismatch cases – those patients with high TDP-43 burden but without cognitive deficits – clusterin expression was increased in gray matter neurons, compared to controls and ALS cases with cognitive decline." (PMID 33192447, 2020). "At variance, we observed a decrement of CLU, IGHG3, and LMW IGLC1 in A in comparison to Y and C. Among these proteins, CLU is known to enhance amyloid clearance and modulate neuroinflammation in mild cognitive impairment." (PMID 33260845, 2020). "High glial expression of clusterin in the patients with TDP‐43 pathology and cognitive deficits could also reflect high levels of reactive gliosis resulting from axonal degeneration and cell death." (PMID 31386770, 2020). "In doing this, we demonstrate spatial expression differences in clusterin between cases with cognitive deficits and mismatch cases without cognitive manifestations, highlighting an important protective mechanism." (PMID 31386770, 2020). "We observed a weakly positive association between plasma clusterin and MMSE, suggesting a weakly negative association between plasma clusterin and severity of cognitive impairment." (PMID 23209684, 2012). "However, HspB8, while statistically significantly upregulated in the white matter glia of ALS cases with TDP‐43 pathology compared to non‐neurological controls, unlike clusterin, was not differentially regulated between individuals with or without cognitive deficits." (PMID 31386770, 2020).